VIP (vasoactive intestinal peptide)
Diseases named in the same sentence as VIP in open-access papers (continued):
Sharing a sentence is not in itself a finding about the gene and the disease.
ulcerative colitis (8 papers, 2019 to 2024). An inflammatory bowel disease involving the mucosal surface of the large intestine and rectum. "More samples, are needed to identify the expressions of miR-30c and VIP among active ulcerative colitis patients and healthy control individuals." (PMID 38342939, 2024). "Also, it would be better to compare miR-30c and VIP expression levels of remission state patients to active ulcerative colitis patients, which would provide more information in the process of ulcerative colitis." (PMID 38342939, 2024). "However, the expression levels of VIP in the colons of the active ulcerative colitis patients was significantly higher than that in normal controls." (PMID 38342939, 2024). "Tight junction proteins on the intestinal epithelium may be the key mechanism in treating sleep-fragmented ulcerative colitis mice with EA, which influences VIP through the VPAC2 and further regulates intestinal mucosa immunity." (PMID 36101343, 2022). "Conversely, in a model of ulcerative colitis, VIP reliably restored mitochondrial function, with equivalent efficacy to super oxide dismutase and dimethyl sulphide, unveiling a novel free-radical-scavenging property of VIP." (PMID 35563181, 2022).
viral infection (8 papers, 2013 to 2025). "Recent studies have demonstrated that inhibition of VIP signaling has a favorable outcome in viral infection and lymphoma models by enhancing CD8+ T cell proliferation and function." (PMID 36650220, 2023). "This indicates that VIP may also have a therapeutic effect on other viral infections by not only changing the receptors used by SARS-CoV-2 but also the replication pathway." (PMID 40141308, 2025). "The same authors also described how VIP reduces viral replication by inhibiting transcription factors SREBPs and NF-kB, which may be another way viral infection can be downscaled." (PMID 40141308, 2025). "Given the homology between human and murine CMV, and the sequence identity between murine and human VIP, the clinical use of a VIP antagonist may be a novel approach to enhance innate and adaptive cellular immunity to vaccines and viral infection in patients." (PMID 23723978, 2013). "The resistance of VIP-KO mice to mCMV infection suggests that physiological VIP signaling during viral infection suppresses innate and/or adaptive antiviral immunity in addition to its well-described pleiotropic effects in regulating gastrointestinal function, cardiovascular tone, and behavior." (PMID 23723978, 2013). "Inhibition of VIP signaling has been shown to increase CD8+ T cell proliferation and function in viral infection and lymphoma." (PMID 36650220, 2023). "Pharmacological inhibition of VIP signaling has shown beneficial effects in increasing proliferation and reducing PD-1 expression on CD8+ and NK T cells in viral infection and lymphoma." (PMID 36650220, 2023). "Our results indicate that that VIP is negative regulator of VPAC1 expression on immature myeloid cells in the absence of viral infection." (PMID 29137229, 2017). "It has previously been shown that MDSCs in the tumor microenvironment are capable of inhibiting activation and proliferation of T cell cells, however, the role of MDSCs and VIP during viral infection is has not been previously characterized." (PMID 29137229, 2017).
Autoimmunity (7 papers, 2016 to 2022). The occurrence of an immune reaction against the organism's own cells or tissues. "Fourth, the focus and conclusions of the current study are orthogonal to previous studies that examined the suppression of autoimmunity by native VIP, or studies that examined the activity of VIP-R antagonists as tumor cytostatic drugs." (PMID 36302761, 2022). "Since then, information on the important role VIP plays in inflammation and autoimmunity continues to accumulate." (PMID 31861827, 2019). "VIP profoundly affects innate and adaptive immunity, and in models of autoimmunity exerts immune modulatory activities." (PMID 31619964, 2019). "VIP effects on inflammatory-mediated autoimmune disorders are elicited, in large measure, by induction of Tregs through tolerogenic DCs." (PMID 31619964, 2019). "The importance of endogenous VIP in the regulation of inflammation and autoimmunity has been confirmed in knockout (KO) mouse models showing altered immune responses." (PMID 31861827, 2019). "While VIP was identified more than four decades ago68, the effects of VIP on immunity were studied by Delgado69,70, and Smally71 starting in 1999 and leading to a 2006 publication that defined the ability of VIP to induce tolerogenic dendritic cells and Tregs that limit autoimmunity and GvHD72." (PMID 36302761, 2022). "The experimental data explained above demonstrate the VIP/VPAC receptor axis as an important endogenous mediator involved in anti-inflammatory and autoimmunity responses in RA." (PMID 31695683, 2019).
bipolar disorder (7 papers, 2010 to 2026). A disorder of the brain that causes unusual shifts in mood, energy, activity levels and the ability to carry out day-to-day tasks. "Specifically, on the one hand, CLOCK and VIP variants appear to be selectively associated with bipolar disorders." (PMID 36833279, 2023). "SCZ, bipolar disorder (BD), and major depressive disorder (MDD) exhibited highly correlated association profiles, including VIP (13 clusters) and MGE-derived interneurons." (PMID 41446173, 2025). "Circadian gene polymorphisms in CLOCK and VIP, and NR1D1, ARNTL and PER3 have previously been associated to human bipolar disorder." (PMID 20856823, 2010). "Only with the network approach, HCN2’s gene scores in Exc_L2-3 were positively correlated with bipolar disorder PRS, and its expression in Exc_L2-3 showed positive correlations with other excitatory neuron populations but negative correlations with VIP and SST interneurons (In_VIP and In_SST)." (PMID 40053590, 2025).
carcinoid syndrome (7 papers, 2019 to 2025). "Other functioning pancreatic NETs are extremely rare and may secrete vasoactive intestinal peptide (VIP), glucagon, somatostatin, or serotonin (carcinoid syndrome)." (PMID 34220719, 2021). "The carcinoid syndrome (CS) becomes manifest when vasoactive substances from the tumors, such as serotonin, tachykinins, bradykinins, kallikrein, histamine, vasoactive intestinal peptide (VIP), prostaglandins, and substance P enter the systemic circulation escaping hepatic degradation." (PMID 33494283, 2021).
Cluster headache (7 papers, 2002 to 2024). A type of headache characterized by repeated attacks of unilateral pain lasting 15 to 180 minutes and associated with local autonomic signs. "VIP has been historically been implicated in the biology of cluster headache, because of its role in mediating cranial autonomic symptoms, and a study suggesting its release during spontaneous cluster attacks." (PMID 38887982, 2024). "PACAP and VIP triggering rates in episodic cluster headache in bout and in chronic cluster headaches were equivalent between the two peptides in one study." (PMID 38887982, 2024). "Further studies are needed to investigate the role of VIP and the parasympathetic system in cluster headache." (PMID 37143998, 2023). "Recent studies suggested an important role for pituitary adenylate cyclase-activating polypeptide (PACAP) and vasoactive intestinal polypeptide (VIP) in the pathogenesis of cluster headache." (PMID 37143998, 2023). "In the cCH group, seven out of 15 (47%) participants reported cluster headache after either PACAP or VIP infusion." (PMID 37143998, 2023). "A total of six out of 14 (43%) eCHA participants reported cluster headache after PACAP infusion, while five out of 14 (36%) eCHA participants reported cluster headache after VIP infusion." (PMID 37143998, 2023). "Pituitary adenylate cyclase-activating peptide (PACAP) and vasoactive intestinal peptide (VIP) provoked cluster headache attacks in individuals with episodic cluster headache during their active phase and individuals with chronic cluster headache." (PMID 37143998, 2023). "Clinical characteristics of PACAP- and VIP-induced cluster headache." (PMID 37143998, 2023). "Interestingly, PACAP levels are elevated in migraine attacks, but VIP levels are only elevated if there are CAS associated, and both are elevated in the cranial circulation in cluster headache, a condition in which CAS are necessary for diagnosis." (PMID 37569369, 2023). "In cluster headache there is an additional release of vasoactive intestinal peptide (VIP)." (PMID 12805934, 2002). "In the present study, we found no changes in plasma VIP during PACAP- and VIP-induced cluster headache." (PMID 37143998, 2023).
Cognitive impairment (7 papers, 2018 to 2023). Abnormal cognition is characterized by deficits in thinking, reasoning, or remembering. "The progeny of VIP-deficient female mice show marked cognitive impairment in hippocampal-dependent tasks." (PMID 35625355, 2022). "Indeed, PACAP deficient mice display impaired recognition memory and VIP deficient mice exhibit cognitive deficits." (PMID 32765225, 2020). "VIP is another ligand for VPAC2, and Vip-deficient mice display a decline in hippocampus-dependent associative memory, a cognitive impairment frequently observed in patients with SCZ." (PMID 37181653, 2023). "Supporting this idea, the AP broadening in I-S3 cells occurred in parallel with cognitive deficits in VIP-eGFP mice, and both variables showed a strong correlation with animal age, suggesting a causal connection." (PMID 33173468, 2020). "Therefore, neuroprotective and immunomodulatory capacities of VIP make this neuropeptide an attractive candidate for the treatment of cognitive deficits in AD." (PMID 32765225, 2020). "We also found that the serum VIP levels of PD and some non-motor symptoms, such as cardiovascular symptoms and mood/cognition disorders, had a certain correlation, the most important being mood/cognition disorders." (PMID 34566619, 2021).
endometriosis (7 papers, 2012 to 2025). The growth of functional endometrial tissue in anatomic sites outside the uterine body. "Compared with women without endometriosis, PGP9.5 (a highly specific pan-neuronal marker), NPY (a marker of sympathetic nerve fibers), and VIP (a marker of parasympathetic nerve fibers) positive nerve fibers are decreased in the isthmus of the oviduct of endometriosis patients." (PMID 32145751, 2020). "In deep infiltrating endometriosis, 20% of HRH1-positive nerves colocalized with substance P, and 40% showed colocalization with both tyrosine hydroxylase and VIP." (PMID 41516088, 2025). "That’s because, in this study only minimal-mild endometriosis patients are placed in the case group and PGP 9.5 is combined with the other markers like VIP (vasoactive intestinal peptide) and SP (subtance P)." (PMID 24639773, 2013). "Sensitivity for minimal to mild endometriosis was 95% with use of combined analysis of neural markers PGP9.5, VIP, and SP." (PMID 23093966, 2012). "Notably, in women with endometriosis, there appears to be an elevated presence of neuropeptide Y (NPY) and vasoactive intestinal peptide (VIP) fibers within the functional layer of the endometrium." (PMID 38592287, 2024).
chronic obstructive pulmonary disease (6 papers, 2011 to 2025). A chronic and progressive lung disorder characterized by the loss of elasticity of the bronchial tree and the air sacs, destruction of the air sacs wall, thickening of the bronchial wall, and mucous accumulation in the bronchial tree. "Stable analogs of vasoactive intestinal peptide (VIP) have been proposed as novel line of therapy in chronic obstructive pulmonary disease (COPD) based on their bronchodilatory and anti-inflammatory effects." (PMID 24069452, 2013). "Similar to our results, stimulation of the large intestine by gavage of mannitol or rhubarb significantly increases VIP both in the intestine and lung of chronic obstructive pulmonary disease (COPD) rats and asthmatic mice and reduces lung histopathological changes." (PMID 36350149, 2022). "Inflammatory diseases such as chronic obstructive pulmonary disease increase SMG innervation with nerve terminals containing substance P and VIP." (PMID 36108628, 2022).
periodontitis (6 papers, 2013 to 2024). An acute or chronic inflammatory process that affects the tissues that surround and support the teeth. "Non-surgical periodontal treatment in these patients resulted in an improvement in the periodontal condition, accompanied by a reduction in the levels of VIP in periodontitis sites compared to those found in clinically healthy sites." (PMID 23599812, 2013). "Nerve fibers positive for VIP have been identified in gingival tissue from both normal and periodontitis-affected sites." (PMID 23599812, 2013). "In periodontitis subjects, VIP is significantly elevated in periodontitis-affected sites compared with the levels in clinically healthy sites." (PMID 23599812, 2013). "Increased VIP in periodontitis sites decreased significantly after treatment." (PMID 35978739, 2022). "A significant increase in VIP in periodontitis sites could be because LPS is a potent stimulus for inducing VIP production and secretion in vitro." (PMID 35978739, 2022). "The study documented that certain neuropeptides including substance P (SP), NPY, vasoactive intestinal polypeptide (VIP), and more pronouncedly the calcitonin gene-related peptide (CGRP) were positively involved in bone metabolism and periodontitis." (PMID 38196480, 2024). "Five neuropeptides (SP, CGRP, VIP, NKA, and NPY) were assessed to evaluate their role in the pathogenesis of periodontitis." (PMID 35978739, 2022). "SP, CGRP, NPY, and VIP immune reactivity in periodontitis gingiva but no discernable variations in distribution when compared to clinically healthy sites." (PMID 35978739, 2022). "Vasoactive Intestinal Peptide (VIP), and Neuropeptide Y (NPY) in saliva (but interestingly not in serum) could potentially be gender-specific salivary biomarkers for periodontitis, regardless of psychological stress." (PMID 31890650, 2019).
phaeochromocytoma (6 papers, 2011 to 2024). "In conclusion, the current report describes a very rare case of WDHA syndrome caused by a VIP-positive pheochromocytoma." (PMID 25081061, 2014). "In this report, we describe a case of WDHA caused by a VIP-positive pheochromocytoma." (PMID 25081061, 2014). "Based on histology, there are two subtypes for these VIP-secreting pheochromocytomas: the composite form (mixed pheochromocytoma and ganglioneuroma) and the classic form (pheochromocytoma only)." (PMID 25081061, 2014). "Such a typical characteristic of pheochromocytoma was probably masked by the vasodilative effect of VIP and severe dehydration due to diarrhea." (PMID 25081061, 2014). "According to the IHC staining, the current case can be diagnosed as a VIP-secreting pheochromocytoma." (PMID 25081061, 2014). "For example, cortisol excess caused by adrenocorticotrophic hormone (ACTH) or corticotrophin releasing hormone (CRH) secretion by phaeochromocytoma has been described as has symptomatic vasoactive intestinal peptide (VIP) and growth hormone-releasing hormone (GHRH) secretion." (PMID 37761307, 2023). "In addition, this was also reported for the first time that a VIP-positive pheochromocytoma had significant effects on bone metabolism in the patient." (PMID 25081061, 2014). "Both the phaeochromocytoma and non phaeochromocytoma components were capable of secreting VIP." (PMID 23587063, 2013). "However, VIP was also positive in phaeochromocytoma cells occasionally." (PMID 23587063, 2013). "In addition to secreting the catecholes dopamine, epinephrine and norepinephrine, numerous other hormones have been isolated from pheochromocytomas including adrenocorticotropin, vasoactive intestinal peptide, neuropeptide Y, IL-6, calcitonin, and chromogranin A." (PMID 21843357, 2011).
sarcoidosis (6 papers, 2012 to 2023). Sarcoidosis is a multisystemic disorder of unknown cause characterized by the formation of immune granulomas in involved organs. "The scientific evidence clearly suggests VIP as a potential treatment option for Sarcoidosis: the system has been able to retrieve the main receptor of VIP and its relevance in the inflammation process." (PMID 24416311, 2014). "Our methodology confirmed the result of an open clinical phase II study, where we treated 20 patients with histologically proven Sarcoidosis and active disease with nebulized VIP for 4 weeks." (PMID 24416311, 2014). "Other recent studies also support the immunosuppressive roles of VIP because VIP relieves collagen-induced arthritis and sarcoidosis by inducing CD4+CD25+Foxp3+ TReg cells from CD4+CD25− T cells." (PMID 22496728, 2012). "Indeed, the first translational use of VIP for regulation of immune conditions was tested with inhaled VIP for inflammatory sarcoidosis which increased Treg numbers and function from T cells in bronchoalveolar lavages." (PMID 31619964, 2019). "Recent study indicated that inhaled VIP exerts immunoregulatory effects in sarcoidosis." (PMID 25101851, 2014). "Enriched genes including MPO (myeloperoxidase), CXCL11, IL1A, CXCL10, FCGR3B, IL1B, TTN (titin), BATF2, VIP (vasoactive intestinal peptide), TLR3, CCR2, TLR7, and CR1 wereclosely related to sarcoidosis." (PMID 38137330, 2023). "Vasoactive intestinal peptide (VIP) inhalation seemed to reduce cough in sarcoidosis in one small open clinical phase II study, but has never been investigated in a randomized setting." (PMID 32024123, 2020). "This study is the first to show that VIP has clear, positive, immune-regulatory effects in sarcoid patients without any obvious side effects and without systemic immuno-suppression." (PMID 24416311, 2014).
airway hyperresponsiveness (5 papers, 2011 to 2018). "Airway hyperresponsiveness is also related to a lower release of smooth muscle relaxants, such as adrenaline, vasoactive intestinal peptide and prostaglandin E2 and I2 (PGE2 and PGI2, respectively)." (PMID 30814952, 2018). "Our findings are in line with evidence demonstrating an increase of SP, CGRP, and VIP after nasal allergen challenge and in airway hyperresponsiveness." (PMID 21245958, 2011). "This lends support for VIP as a novel medicine to treat a subset of asthmatics who have airway hyperresponsiveness in particular to sodium metabisulfite which is ubiquitous in red wine, a product of the yeast Saccaryomyces cerevisiae in beer, and is often used in to preserve sundry foods." (PMID 22103391, 2011).
carcinoids (5 papers, 2015 to 2025). "Current US Food and Drug Administration (FDA)–approved indications for the use of octreotide in adults include acromegaly, severe diarrhea and/or flushing secondary to carcinoid tumors, and severe diarrhea secondary to VIP‐secreting tumors." (PMID 40629899, 2025). "Octreotide is FDA‐approved for adults with severe diarrhea secondary to carcinoid tumors, and severe diarrhea secondary to VIP‐secreting tumors." (PMID 40629899, 2025). "We evaluated the patient for carcinoid tumor small bowel recurrence by screening for gastrin, vasoactive intestinal peptide, and 24 h urine 5-hydroxytryptamine levels; all of these were within normal limits." (PMID 40126291, 2025). "However, her levels of gastrin, vasoactive intestinal peptide, and 5-hydroxytryptamine from 24 h urine assessing for recurrent carcinoid were all within normal limits." (PMID 40126291, 2025). "Both functioning NENs—such as glucagonomas, ACTH-secreting tumors, serotonin-secreting carcinoids, calcitonin-secreting neoplasms, and VIP- and/or dopamine-secreting tumors —and non-functioning NENs have been implicated in thrombotic events." (PMID 39857994, 2025).